GLIPR1L1 (GLIPR1 like 1)
Description:
Required for optimal fertilization at the stage of sperm-oocyte fusion, plays a role in optimizing acrosome function, the translocation of IZUMO1 during the acrosome reaction and the fertilization process. Component of epididymosomes, one type of membranous microvesicules which mediate the transfer of lipids and proteins to spermatozoa plasma membrane during epididymal maturation. Also component of the CD9-positive microvesicules found in the cauda region.
Synonyms: MGC26856; ALKN2972; PRO7434
Tractability: Antibody: UniProt places it where antibodies can reach, with medium confidence; UniProt predicts a signal peptide or a membrane-spanning region; its Gene Ontology location is reachable by antibodies, with medium confidence.
Gene: Protein-coding gene on chromosome 12 (75,334,670 to 75,370,560, forward strand). Ensembl gene ENSG00000173401.
Subcellular location: Cytoplasmic vesicle, secretory vesicle, acrosome; Cell membrane; Membrane raft; Secreted
Gene Ontology:
Biological process: fusion of sperm to egg plasma membrane involved in single fertilization
Cellular component: acrosomal vesicle; extracellular region; membrane raft; plasma membrane; protein complex involved in cell-cell adhesion
Genetic constraint (gnomAD): Loss-of-function variants: 7 observed, 7.9 expected, observed/expected ratio (o/e) 0.89, 90% interval 0.5 to 1.62. That is too few expected variants to judge how well the gene tolerates losing a copy. Missense variants: 111 observed, 115.23 expected, observed/expected ratio (o/e) 0.96, 90% interval 0.82 to 1.13. Synonymous variants: 30 observed, 39.95 expected, observed/expected ratio (o/e) 0.75, 90% interval 0.56 to 1.02.
Homologues: Orthologues: chimpanzee GLIPR1L1 (99% identical), macaque GLIPR1L1 (86% identical), pig GLIPR1L1 (62% identical), dog GLIPR1L1 (57% identical), guinea pig GLIPR1L1 (57% identical), rat Glipr1l1 (46% identical), mouse Glipr1l1 (45% identical), mouse Glipr1l3 (45% identical), zebrafish glipr1a (40% identical), zebrafish glipr1b (33% identical), Caenorhabditis elegans scl-1 (24% identical), Caenorhabditis elegans scl-14 (24% identical), and 47 more. Paralogues in human: GLIPR1 (40% identical), GLIPR1L2 (36% identical), CRISPLD2 (29% identical), R3HDML (28% identical), PI15 (28% identical), CLEC18B (27% identical), CRISP3 (27% identical), CRISPLD1 (27% identical), CLEC18A (27% identical), CLEC18C (27% identical), CRISP2 (27% identical), CRISP1 (22% identical), and 1 more.
Diseases named in the same sentence as GLIPR1L1 in open-access papers:
GLIPR1L1 is named in the same sentence as 4 diseases in open-access papers, as found by Europe PMC text mining. Sharing a sentence is not in itself a finding about the gene and the disease. The quoted sentences say what the papers report.
glioma (1 paper, 2020). A benign or malignant brain and spinal cord tumor that arises from glial cells (astrocytes, oligodendrocytes, ependymal cells). "GLIPR1L1 participates in the encoding of the glioma pathogenesis-related protein (GLIPR1), a member of the CAP superfamily, and could promote the proliferation, survival, and invasion of glioma cells and inhibit apoptosis." (PMID 33230136, 2020).
Obesity (1 paper, 2016). Accumulation of substantial excess body fat. "The genes within 2 Mb of the signal, include RP11-81H3.2, CAPS2, GLIPR1, GLIPR1L1, GRLPR1L2, and KRR1, none of which is an obvious candidate gene for involvement in obesity or T2D." (PMID 27623749, 2016).
tumor (4 papers, 2015 to 2021). "Other tumor suppressor genes which inhibit cell migration, metastasis, invasion and that were induced by estradiol in pericytes include GLIPR1L1; ZNF582-AS1 (a novel lncRNA); DACT1." (PMID 34571963, 2021). "So far, we have performed experimental validation on four of the identified candidates (GLIPR1L1, GHSR, CEACAM6, and CCR9, of which we here report on CCR9) using additional tumor cell lines and antigen-specific CTL clones and in all cases we could confirm their immune-modulatory function." (PMID 25691366, 2015).
GLIPR1L1 also shares sentences with these, for which no sentence is quoted: breast carcinoma (1 paper).